OPN1SW (opsin 1, short wave sensitive)
Description:
G protein-coupled photoreceptor that selectively activates G(i) proteins in response to short-wavelength (blue-violet) light, thereby decreasing intracellular cAMP levels (PubMed:2937147, PubMed:6140680, Ref.10). Activation occurs when the opsin-bound cis-retinal chromophore absorbs a photon and isomerizes to all-trans-retinal, inducing a conformational change in the opsin that triggers a G protein-mediated phototransduction cascade (Ref.10). Required for the maintenance of cone outer segment organization in the ventral retina, but not essential for the maintenance of cone photoreceptor function (By similarity). Involved in ensuring the correct abundance and localization of retinal membrane proteins (By similarity). Mediates visual perception of blue light. May contribute to increased spectral sensitivity under dim light conditions (By similarity). Is not UV-sensitive (By similarity).
Synonyms: BOP; BCP; CBT
Tractability: Small molecule: it belongs to a druggable protein family. Antibody: UniProt places it where antibodies can reach, with high confidence; its Gene Ontology location is reachable by antibodies, with high confidence; UniProt predicts a signal peptide or a membrane-spanning region.
Gene: Protein-coding gene on chromosome 7 (128,772,485 to 128,775,794, reverse strand). Ensembl gene ENSG00000128617.
Subcellular location: Cell membrane; Photoreceptor outer segment membrane; Photoreceptor inner segment; Cytoplasm, perinuclear region
Pathways (Reactome):
Signal Transduction: G alpha (i) signalling events; Opsins
Disease: Defective visual phototransduction due to OPN1SW loss of function
Sensory Perception: The retinoid cycle in cones (daylight vision)
Gene Ontology:
Molecular function: protein binding; G protein-coupled photoreceptor activity; signaling receptor activity; G protein-coupled receptor activity
Biological process: absorption of visible light; cellular response to UV-A; visual perception; cellular response to light stimulus; G protein-coupled receptor signaling pathway; phototransduction; signal transduction; transducin-mediated opsin signaling pathway
Cellular component: perinuclear region of cytoplasm; plasma membrane; cone photoreceptor disc membrane; photoreceptor disc membrane; photoreceptor inner segment; photoreceptor outer segment; ciliary membrane; membrane
Genetic constraint (gnomAD): Loss-of-function variants: 25 observed, 33.9 expected, observed/expected ratio (o/e) 0.74, 90% interval 0.54 to 1.03. The upper end of that interval is the gene's LOEUF score, 1.03, which puts it in group 4 of 6, group 1 being the genes least tolerant of losing a copy. Missense variants: 424 observed, 472.11 expected, observed/expected ratio (o/e) 0.9, 90% interval 0.83 to 0.97. Synonymous variants: 190 observed, 181.51 expected, observed/expected ratio (o/e) 1.05, 90% interval 0.93 to 1.18.
Homologues: Orthologues: chimpanzee OPN1SW (100% identical), macaque OPN1SW (97% identical), dog OPN1SW (89% identical), rat Opn1sw (88% identical), pig OPN1SW (86% identical), rabbit OPN1SW (86% identical), guinea pig OPN1SW (86% identical), mouse Opn1sw (86% identical), tropical clawed frog opn1sw (77% identical), zebrafish opn1sw1 (60% identical). Paralogues in human: RHO (46% identical), OPN1MW (44% identical), OPN1MW2 (44% identical), OPN1MW3 (44% identical), OPN1LW (43% identical), OPN3 (26% identical), OPN4 (26% identical), RRH (21% identical), OPN5 (18% identical).
Diseases named in the same sentence as OPN1SW in open-access papers:
OPN1SW is named in the same sentence as 21 diseases in open-access papers, as found by Europe PMC text mining. Sharing a sentence is not in itself a finding about the gene and the disease. The quoted sentences say what the papers report.
retinal degeneration (2 papers, 2019 to 2024). Degeneration of the retina. "Furthermore, in 4-week-old Hbs1ltm1a/tm1a mice, western blotting revealed the remarkable decrease of rhodopsin levels but not of Opn1sw, a cone opsin involved in color vision, indicating that the observed retinal degeneration affects mostly rods but not cones at this time point." (PMID 38966981, 2024).
cone-rod dystrophy (1 paper, 2022). Inherited retinal dystrophies that belong to the group of pigmentary retinopathies. "Additionally, a mouse knockout model of BBS5 developed a cone-rod dystrophy as well as displayed mislocalization of cone-specific proteins such as OPN1SW, OPN1MW and GNAT2; we report that OPN1MW and GNAT2 are mislocalized in Bbs10−/− mice." (PMID 36125046, 2022).
glaucoma (1 paper, 2021). Increased pressure in the eyeball due to obstruction of the outflow of aqueous humor. "These 13 glaucoma-associated genes can be divided into three functional groups: phototransduction-related genes (GNGT1, OPN1SW, PDE6A, PDC, CRX, CNGB1, GUCY2F), glutamate receptor (GR) genes (GRIN2B, GRIK3, GRIK4), and 5-hydroxytryptamine receptor (HTR) genes (HTR1A, HTR1E, HTR7)." (PMID 33874942, 2021).
retinal disease (1 paper, 2017). "Moreover, GNAT2 and OPN1SW are cone-specific markers, and the dysregulation of these genes may be related to retinal disease." (PMID 28484645, 2017).
retinitis pigmentosa (1 paper, 2020). Retinitis pigmentosa (RP) is an inherited retinal dystrophy leading to progressive loss of the photoreceptors and retinal pigment epithelium and resulting in blindness usually after several decades. "As expected, expression levels for the cone-specific genes Opn1sw, Opn1mw, and Gnat2 in the Rds mutant retinas at P25 did not deviate from wild type levels since cone degeneration is delayed in this retinitis pigmentosa model." (PMID 32313077, 2020).
tumor (1 paper, 2022). "Likewise, the tumor cells lacked expression of the common PNEC mechanosensor PIEZO2 but showed broad expression of the acid-sensitive channel KCNK3 and opsin OPN1SW, which is expressed only by rare normal PNECs." (PMID 36469459, 2022).
OPN1SW also shares sentences with these, for which no sentence is quoted: liver diseases (9 papers); Cirrhosis (6); infection (6); chronic hepatitis B (4); hepatocellular carcinoma (4); liver cirrhosis (3); Fulminant hepatic failure (2); breast carcinoma (1); carcinoid (1); chronic hepatitis (1); co-infection (1); liver failure (1); liver fibrosis (1); lung carcinoma (1); retinoblastoma (1).